TLR4 (toll like receptor 4)
Diseases named in the same sentence as TLR4 in open-access papers (continued):
Sharing a sentence is not in itself a finding about the gene and the disease.
depression (continued). "TLRs (including TLR4) are upregulated in major depressive disorder patients, while antidepressant treatment downregulates TLRs expression, suggesting that TLRs are critical mediators for antidepressant therapy." (PMID 39749341, 2024). "In the LPS-induced depression model, the use of raspberry ketone supplementation can alleviate depressive behavior through mitigated gut inflammation by inhibiting the TLR-4/NF-κB pathway." (PMID 39749341, 2024). "Studies have provided evidence that TLR4 signaling was upregulated in newly diagnosed patients with depression." (PMID 37917302, 2024). "TLR4, an innate immune receptor recognizing signals from microorganisms or damaged cells, plays a significant role in neuropsychiatric diseases including depression." (PMID 39346901, 2024). "In summary, Fructus arctii mitigates depression by regulating the let‐7e/TLR4/MyD88 pathway, offering new insights into potential depression therapies." (PMID 39538967, 2024). "Upregulation of the TLR4/NF-κB pathway is common in individuals with depression, whereas TLR4 deletion or knockout alleviates neuroinflammation and behavioral abnormalities in mice." (PMID 39346901, 2024). "Paeoniflorin has a wide range of biological activities and can exert anti-inflammatory, antioxidant and immunomodulatory effects through the TLR4-NF-κB signaling pathway, and it is also used in depression and neurological disorders." (PMID 39408592, 2024). "And the antidepressants obviously alleviated CUMS-induced depression-like behavior and exerted considerable neuroprotective effects by regulating the microglial state transition by inhibiting the TLR4/MyD88/NF-κB signaling pathway." (PMID 37917302, 2024). "TLR4, a pattern recognition receptor, has been proved to be mainly expressed in microglia and exerts regulatory roles in linking stress and depression." (PMID 37917302, 2024). "Data from the animal experiment have verified the neuroinflammation-induced depressive-like behavior mediated by the activation of microglia and TLR4 in stress models of depression." (PMID 37917302, 2024). "It is indicated that salidroside regulates inflammation by mediating the TLR4 signaling pathway, which is one of the mechanisms of action in the treatment of depression." (PMID 39770545, 2024). "The present study only preliminarily investigated the effect of acupuncture on ameliorating depression-like behaviors via regulating the neuroinflammation mediated by TLR4 signaling pathway in rats exposed to chronic restraint stress." (PMID 37917302, 2024). "Collectively, these results suggest that Fructus arctii upregulates let‐7e expression and inhibits TLR4 pathway activation in CUMS‐induced depression mice." (PMID 39538967, 2024). "The depressive-like behaviors were reversed with a TLR4 antagonist suggesting that hyperactive TLR4-NF-κB signaling is involved in the pathogenesis of depression." (PMID 37252156, 2023). "In contrast to the conventional drug L-thyroxine for curing hypothyroidism, YJT has an efficacy for attenuating systematic inflammatory responses, related with depression in intestinal TLR4 and Nod2/Pglyrp1 signaling pathways." (PMID 37270649, 2023). "Perhaps the relationship to depression represents an indirect path for TLR4 to influence alcohol consumption." (PMID 37296629, 2023). "We investigated the role of PTEN in regulating FoxO1‐ and TLR4‐mediated neuronal injury in mice with depression." (PMID 37308778, 2023). "In vitro and in vivo experiments confirmed that KJG is an effective treatment for depression by downregulating TLR4 expression to reduce neuroinflammation through the PI3K/AKT/FOXO1 pathway." (PMID 37173696, 2023). "Activation of TLR-4 induces depression-like behavior in animal models and has been proposed as a key factor in the inflammatory theory of depression." (PMID 36768580, 2023). "Several PRRs, toll-like receptor-4 (TLR-4) and NLR family pyrin domain containing 3 (NLRP3), have been implicated in depression." (PMID 37252156, 2023).
depression (continued). "Baicalin significantly reduced the levels of TNF-α, IL-1β, and IL-6 in depression-like hippocampal tissues by upregulating PI3K/AKT/FOXO1 pathway and inhibiting TLR4 expression and so alleviate neuroinflammation-induced depression-like behavior." (PMID 35350754, 2022). "It was found that administration of paeoniflorin can inhibit the activity of the high-mobility group box 1 protein/TLR4/NF-κB pathway and alleviate the level of inflammation in the serum and hippocampus, thereby treating lupus-induced depression." (PMID 36408279, 2022). "The most critical finding of our in vivo study was that Gps improved CUMS-induced depression-like behavior through promoting microglial states into the anti-inflammatory phenotypes likely by inhibiting the TLR4/MyD88/NF-κB signaling pathway." (PMID 35370734, 2022). "Iba1 fluorescence staining showed that LPS‐induced TLR4 activation partially reversed the activation of microglia decreased by n‐3 PUFAs in depression mice." (PMID 36301036, 2022). "Puerarin alleviates HFD/CUMS-induced depression-like behavior by restraining TLR4-related inflammation." (PMID 36358493, 2022). "Further, the increased TLR4 induced by LPS partially reversed the inhibition of n‐3 PUFAs on depression‐like behaviors, microglial activation and inflammatory injury of hippocampal neurons." (PMID 36301036, 2022). "In conclusion, inhibition of HMGB1 release or inhibition of HMGB1/TLR4/RAGE signaling pathway by HMGB1 inhibitors is beneficial for the treatment of depression." (PMID 36388178, 2022). "Changes in TLR4 signaling pathways were discovered in the peripheral circulatory system or central nervous system (CNS) in patients with major depression and depression-like animal models." (PMID 36358493, 2022). "The six predominant targets (TNFα, ESR1, TLR4, PTGS2, MMP9 and NOS3) have been well documented to associate with depression." (PMID 35626632, 2022). "First, LPS upregulated the protein level of TLR4 in hippocampus from n‐3 PUFAs treated depression mice." (PMID 36301036, 2022). "Arctigenin, safflower extract, baicalin, Xiao-Chai-Hu-Tang, puerarin, etc. alleviated depression through TLR4 signaling pathways." (PMID 36408212, 2022). "In the present study, we observed that the inflammatory immune activation accompanied by microglial reactivity, and TLR4/MyD88/NF-κB signaling were activated in a CUMS-induced depression mice model and LPS-exposed BV-2 cells." (PMID 35370734, 2022). "Using a chronic mild stress mouse model of depression, NK cell-derived exosomes carrying miR-207 alleviated symptoms such as depression and decreased pro-inflammatory cytokines, targeted TLR4, and hence an inhibited NF-κB signaling in astrocytes." (PMID 35884901, 2022). "It is reported that stress can induce depression-like behaviours through the HMGB1/TLR4/NF-κB signalling pathway in the hippocampus and PFC." (PMID 35677442, 2022). "Moreover, TLR4 was able to regulate the response of adrenal hormones to stress and inflammatory stimuli, and NF‐κB could disrupt hypothalamic−pituitary−adrenal axis to cause inflammatory response disorder, thereby aggravating the symptoms of depression." (PMID 36301036, 2022). "The expressions of TLR2 and TLR4 on Th17 (IL-17+CD4+ T cells)/Tc-17 (IL-17+CD8+ T cells) were significantly upregulated in MS with major depressive disorder (MDD) compared with MS." (PMID 34790205, 2021). "Elevated TLR4 mRNA and protein levels are found in brain tissue from animal models of depression, and in the peripheral blood of depressed patients [15,26,]." (PMID 34226490, 2021). "Subsequently, the effects of SJE on alleviating depression and anxiety by inflammatory response were investigated by measuring the expression levels of inflammatory cytokines and key proteins in TLR4/NLRP3 signaling pathways." (PMID 34977127, 2021).
depression (continued). "Changes of TLR4 signaling pathways were found in the peripheral circulation system or the central nervous system (CNS) of patients with major depression and depression-like animal models." (PMID 34975477, 2021). "In CNS, TLR4 is one of the most widely studied proteins, which is mainly expressed in microglia and its activity can affect the depression-like behavior." (PMID 34977127, 2021). "Animal studies show that experimental models of depression affect the intestinal barrier allowing the bacteria translocation and inducing a neuroinflammatory response through TLR-4 activation in the brain." (PMID 34934041, 2021). "In conclusion, puerarin treatment reversed HFD/CUMS-induced depression-like behavior by inhibiting TLR4-mediated inflammatory damages and phospholipid metabolism disorders." (PMID 34975477, 2021). "In this study, we used colonic tissue to study depression and investigated key factors involved in the TLR4/NLRP3 inflammasome signaling pathway by H&E staining, immunohistochemistry, qPCR, and Western blotting." (PMID 33505499, 2021). "Toll-like receptor 4 (TLR4) is the primary receptor for the production of cytokines induced by LPS, and the expression of TLR4 in the hippocampus is upregulated in mice with depression-like behaviors accompanying neuroinflammation." (PMID 34827513, 2021). "In conclusion, RVX in a dose-dependent manner possesses potent ameliorative effects against depression by reducing the oxidative stress and inflammatory process, through the regulation of the TLR4/Myd88/NF-kβ signaling pathway." (PMID 34630092, 2021). "In conclusion, puerarin treatment reverses HFD/CUMS-induced depression-like behavior by inhibiting TLR4-mediated intestine mucus barrier dysfunction and neuro-inflammatory damages via the TLR4/cPLA2/COX-2 pathway." (PMID 34975477, 2021). "RVX, in a dose-dependent manner, possesses potent ameliorative effects against depression by decreasing oxidative stress, inflammation, and regulating the TLR4/Myd88/NF-kβ signaling pathway." (PMID 34630092, 2021). "Mice suffering from chronic stress are more likely to show depression-like behavioral phenotypes, and TLR4 knockout can reduce chronic stress–induced cytokine levels in the mice hippocampus." (PMID 34975477, 2021). "In the present study, we evaluated the protective effect of puerarin on HFD/CUMS-induced depression-like rats and explored the molecular mechanisms based on TLR4-mediated inflammatory responses." (PMID 34975477, 2021). "TLR4 acts as a hub between many neuroimmunological responses and is also thought to mediate inflammatory activity in prolonged stress and depression alongside the hypothalamic-pituitary (HPA)-axis [20,22,23,]." (PMID 34226490, 2021). "Previous findings in a mouse model of depression show that plasma levels of MIP-1β/CCL4 are elevated by stress and linked to elevated hippocampal mRNA expression of TLR4." (PMID 34226490, 2021). "For better understanding the inflammatory processes associated with depression, systematic examination of the role of TLR4 in stress‐induced depression is needed." (PMID 31945269, 2020). "In this study, the effects of TLR4 on depressive‐like behaviors were investigated in an animal model of depression induced by CSDS." (PMID 31945269, 2020). "Both TLR3 and TLR4, have been found in post-mortem brain samples from individuals with depression that died by suicide that suffered from depression." (PMID 31647818, 2019). "Recent studies have shown that the anti-inflammatory effect of baicalin is linked to toll-like receptor 4 (TLR4), which participates in pathological changes of central nervous system diseases such as depression." (PMID 31068207, 2019). "Other studies provide additional evidence that the TLR4/NF-κB pathway is activated in the frontal cortex and the hippocampus in stress-induced depression in mice." (PMID 31139084, 2019).
depression (continued). "Specially, increased damage-associated molecular pattern (DAMP), an active element of the TLR4/NF-κB signal, has been found in stress reaction which was regarded as the major reason of depression." (PMID 29765402, 2018). "Altered TLR-4 signaling has been described in peripheral blood cells and the brain of patients with schizophrenia, bipolar disease, and depression; in postmortem brain of subjects with schizophrenia; and in stress animal models." (PMID 30180869, 2018). "TLR4 signaling pathway has been shown to have a pivotal role in stress-induced neuroinflammation and major depressive disorder." (PMID 30180864, 2018). "Past studies demonstrated that the TLR4 signaling pathway in the CNS and the periphery are associated with activated glycogen synthase kinase-3 (GSK3), a kinase shown to be involved in depression." (PMID 30618863, 2018). "Preclinical studies have shown that TLR4 expression in the prefrontal cortex is enhanced in a stress-based model of depression." (PMID 26415953, 2016). "Abnormalities in Toll-like receptor (TLR) expression in depression have been inferred in part from observed increases in TLR4 levels in peripheral blood mononuclear cells (PBMCs) and postmortem brains of depressed and suicidal patients." (PMID 26415953, 2016). "Hutchinson and colleagues expand on this discussion by exploring the specific contribution of the innate immune pattern recognition receptor Toll-like receptor 4 (TLR4) in the pathophysiology of depression." (PMID 26082681, 2015). "Injection of lipopolysaccharides (LPS) in mice has been shown to induce the expression of innate immune genes through activation of TLR4 in microglia and astrocytes, leading to depression-like behaviors." (PMID 26381263, 2015). "Through use of knockout models as well as pharmacological agonists and antagonists, TLR4 activation has been shown to elicit depression-like symptoms in animal models both behaviorally and physiologically." (PMID 25324715, 2014). "On the other hand, this direct relationship between TLR4 and depression is still not fully understood, although timing and location of TLR4 activation appears to be important." (PMID 25324715, 2014). "The present work points to a role for bacterial translocation and subsequent TLR-4 pathway stimulation in the neuroinflammation induced by an experimental model of depression." (PMID 22053929, 2011). "Now, our results show for the first time increases in expression of and mRNA levels for Toll-like receptor 4 (TLR-4) in the brain cortex in an experimental model of depression in rodents." (PMID 22053929, 2011). "Additionally, raspberry ketone has been shown to reduce gut barrier dysfunction and hamper LPS-induced depression-like behaviors in mice by suppressing TLR-4/NF-κB signaling pathway involving the gut–brain axis and increasing the production of SCFAs." (PMID 40643545, 2025). "In depression mice, GC levels elevate, Toll-like receptor 4 (TLR4) and nuclear factor kappa B (NF-κB) expression in bone marrow mononuclear cells show upregulated, as well as intima-media thickness, HR, plasma cholesterol, triglycerides, and low-density lipoprotein (LDL)-to-HDL ratios are increased." (PMID 41301929, 2025). "TLR4 signaling pathway plays a crucial role in the development of several neuropsychiatric disorders, such as schizophrenia and depression." (PMID 40453654, 2025). "Future large-scale studies are needed to investigate the expression pattern of TLR4 in IBS, whether there are differences in expression between subtypes and the effect of concomitant symptoms such as anxiety and depression on TLR4 expression in IBS." (PMID 39749341, 2024). "Notably, recent research has unveiled a connection between LPS-induced TLR4 activation and depression in mice, particularly concerning deltamethrin-induced disruption of the gut–brain axis." (PMID 38792602, 2024).
depression (continued). "Acupuncture exerted potential antidepressant-like effect that might be mediated in part by suppressing the neuroinflammation induced by TLR4 signaling pathway, which may be a promising treatment target to improve current treatments for depression." (PMID 37917302, 2024). "ACE (specifically EA) is known to exert neuroprotective effects, such as alleviating first-episode major depressive disorder by activating the visual network and reducing depressive-like behaviors in rats under chronic restraint stress by inhibiting TLR4 signaling pathway-induced neuroinflammation." (PMID 39850625, 2024). "Conclusively, the present study provided evidence that the stress-induced activation of neuroinflammation mediated by TLR4 signaling pathway might be the key pathway linking stress and depression." (PMID 37917302, 2024). "Additionally, Soy isoflavones have been found to ameliorate depression-like behaviors by inhibiting hippocampal neuroinflammation and the toll-like receptor 4 (TLR4)/nuclear factor kappa B (NF-κB) signaling pathway." (PMID 38309292, 2024). "HMGB1 binds to TLR4, leading to the recruitment and promotion of NF-κB, thereby activating the transcription of inflammatory cytokines, chemokines, and adhesion molecules, and promoting the development of depression." (PMID 39114351, 2024). "However, stress-induced depression-like behaviors were effectively alleviated by inhibiting microglial activation and neuroinflammation via TLR4 pathways." (PMID 37917302, 2024). "The toll-like receptor 4 (TLR4)/Myeloid differentiation primary response gene 8 (MyD88)/NF-κB pathway is a classical inflammatory signaling pathway involved in the development of depression." (PMID 39484160, 2024). "Some drugs can treat depression through TLR4 and its signaling pathway." (PMID 39749341, 2024). "In addition, the toll-like receptor 4 (TLR4) signaling pathway is involved in the regulation of the body’s immune response and is closely related to the immune inflammatory process of depression." (PMID 39770545, 2024). "Moreover, when MDD patients were successfully treated, the TLR4 levels were found to be restored, suggesting their potential role in depression." (PMID 39839132, 2024). "Several mechanisms involved in spike protein have been proposed at the mice level such as TLR2-mediated depression, TLR4-mediated cognitive dysfunction, and anxiety mediated by non-cell autonomous hippocampal neuronal cell deaths by inducing IL-1β from glial cells." (PMID 38834668, 2024). "Our study demonstrated that sinisan significantly alleviated the symptoms of IBS-D and ameliorated intestinal dysfunction and depression-like behavior in mice, which may be achieved by inhibiting the TLR4/MyD88/NF-κB pathway." (PMID 39408592, 2024). "TLR4 protein levels increase in the hippocampus of mice subjected to chronic social stress and positively correlated with severity of depression‐like symptoms, whereas treatment with the antidepressant fluoxetine downregulated TLR4 expression and alleviated depression‐like behavior." (PMID 37308778, 2023). "Another study found that inhibition of TLR4 expression could reduce neuroinflammation‐induced depression‐like behavior." (PMID 36301036, 2022). "Besides, much evidence suggests an impact of toll-like receptor 4 (TLR4) signaling on depression while it is rarely reported in PPD." (PMID 36408212, 2022). "Other studies have specifically investigated TLR4-NF-κB pathways in depression." (PMID 35782423, 2022). "Brain-derived neurotrophic factor (BDNF)-tropomyosin receptor kinase B (TrkB) pathway, mitogen-activated protein kinase (MAPK) pathway, glycogen synthase kinase-3 (GSK-3) pathway, toll-like receptor 4 (TLR4) pathway, etc. are involved in the pathological process of depression." (PMID 35923544, 2022).